CXCL3 (C-X-C motif chemokine ligand 3)
Diseases named in the same sentence as CXCL3 in open-access papers (continued):
Sharing a sentence is not in itself a finding about the gene and the disease.
tumor (continued). "Current research has shown that CXCL3, CXCL5, and CXCL8 were CXC chemokines strongly associated with tumor angiogenesis." (PMID 35795552, 2022). "CXCL3 levels were increased in CRC patients, with plasma CXCL3 levels associated with tumor progression and an unfavorable CRC prognosis." (PMID 35664357, 2022). "Multiple studies have found CXCL3 to participate in the development of many inflammatory and autoimmune diseases and the progression and metastasis of many tumor types." (PMID 35664357, 2022). "The CXCL3/CXCR2 signaling pathway is associated with a variety of diseases and is important in tumor development and progression." (PMID 35802745, 2022). "In our previous research, we found that CXCL3 affects the biological behavior of tumor cells in the form of autocrine or paracrine." (PMID 34870709, 2021). "CXCL3 plays extensive roles in tumorigenesis in various types of human cancers through its roles in tumor cell differentiation, invasion, and migration." (PMID 34870709, 2021). "KRAS-mediated repression of interferon regulatory factor 2 (IRF) results in the high expression of the chemokine C-X-C motif ligand 3 (CXCL3), which induces MDSCs that express C-X-C motif chemokine receptor 2 (CXCR2) as the receptor of CXCL3 in tumor tissues." (PMID 34359568, 2021). "We first evaluated the mRNA expression of CXCL3 in HNSCC from the TCGA database and found that the expression level of CXCL3 in tumor tissues was significantly higher than that in normal tissues." (PMID 34870709, 2021). "We also performed further experiments in vivo and in vitro to evaluate the expression of CXCL3 in a human head and neck tissue microarray and the underlying effect mechanisms of CXCL3 on the tumor biology of HNSCC tumor cells." (PMID 34870709, 2021). "Among them, the UALCAN database showed that CXCL3 was related to the trait of histological types in ESCA and READ, GPR44 (PTGDR2) was associated with tumor grade in ESCA and NPBWR1 was related to patients’ age in ESCA and READ." (PMID 33552958, 2020). "The effects of curcumin and CM-NP on the expression of CXCL3, a tumor metastatic marker, in GSCs were studied." (PMID 32430842, 2020). "Conversely, the mRNA expression of S100A14, IL1A, CCL2, CXCL3 and CXCL5 in tumor tissues derived from S100A14-deficient mice was significantly reduced compared with those from their WT counterparts." (PMID 32483412, 2020). "High expression of CXCL3 was detected in premalignant adenomas and CRC tissue, and CXCL3 significantly downregulated in liver metastasis compared with the primary tumor." (PMID 32351322, 2020). "Interleukin 8 (CXCL8), CXCL3, and CXCL1 are CXC chemokines that are strongly associated with tumor angiogenesis." (PMID 32462020, 2020). "Consistent with previous research, we also found that the transcription levels of CXCL3 in HNSCC samples were remarkably increased when compared with non-tumor tissue." (PMID 33489879, 2020). "More importantly, high expression of CXCL3, ELF5, and TIMP1 was significantly associated with lymphatic invasion, distance metastasis, and advanced tumor stage." (PMID 29209625, 2017). "Our further experiment about validation and clinicopathologic analysis revealed that high expression of CXCL3, ELF5, and TIMP1 was significantly associated with lymphatic invasion, distance metastasis, and advanced tumor stage." (PMID 29209625, 2017). "It is worth noting that among the genes in Set A whose expression is down-regulated abound those with tumor-inhibitory activity (e.g., Pag1, PadI4, Lats2, and Cxcl3), while among the up-regulated genes are present tumor facilitators (e.g., Rab18, Dek)." (PMID 27965576, 2016). "Sorted CD133+/− PLC/PRF/5 cells were cultured in suspension in CDM, and CXCL3 was then stably knocked down in both populations to observe their tumor-sphere formation ability." (PMID 27255419, 2016).
tumor (continued). "CXCL3 was still firmly expressed by tumor cells in both Calu-6 and SK-MES tumors from myeloablated and hrIL-27-treated mice, while a faint IFNγ production was only detected in the latter." (PMID 25638163, 2015). "As observed for PDT-treated tumor cell lines, Cxcl2, Cxcl3 and Il6 were among the most strongly upregulated genes, although we cannot exclude that these cytokines were expressed by stromal cells in the tumor microenvironment or tumor-associated immune cells." (PMID 21738796, 2011). "In vivo, CXCL3 overexpression significantly promoted tumor growth in nude mice." (PMID 41259383, 2025). "CXCL3 is known to recruit N2 TANs, which then contribute to tumor angiogenesis." (PMID 40751595, 2025). "Immune-related genes, such as chemokine (Cxcr2), C-type lectin (Clec4e), chemokine ligand (Cxcl3), tumor growth-related genes, galectin-7 (Lgals7), and matrix metallopeptidase 8 (Mmp8), were downregulated by colonization of B. plebeius in colon tissues of the mice exposed to AOM/DSS." (PMID 39804065, 2025). "Recent studies indicate that CXCL3 is overexpressed in multiple malignancies and may contribute to tumor initiation and progression by acting within the tumor microenvironment." (PMID 41259383, 2025). "Similarly, CXCL3 plays an important role in various human cancers by regulating the differentiation, invasion, and migration of tumor cells." (PMID 40179015, 2025). "Studies have shown that knocking down CXCL3 restores tumor sensitivity to anti-PD-1 therapy." (PMID 41226585, 2025). "Moreover, CXCL3 derived from both tumor cells and stromal cells was shown to promote the malignant behaviour of tumor cells through activation of the PI3K/AKT/mTOR signalling pathway." (PMID 41259383, 2025). "Our study suggested that inhibiting CCL20 or CXCL3 can directly inhibit tumor progression." (PMID 40179015, 2025). "Moreover, CXCL3 secreted by hepatic stromal LX-2 cells was also shown to enhance tumor cell malignancy." (PMID 41259383, 2025). "In summary, our experiment showed that chemokine CXCL3 is highly expressed in COAD, and its high-level expression is closely associated with several tumor-associated clinicopathological parameters, chemokines, genes, signaling pathways and immunocyte recruitment." (PMID 38031087, 2023). "Our findings indicated that activation of MAPK/ERK signal pathway controlled by upregulation of CXCL3 might be one of the key determinants in tumor biology of COAD." (PMID 38031087, 2023). "Protein-protein interaction (PPI) analysis revealed that cyclin B1 (CCNB1), mitotic arrest deficient 2 like 1 (MAD2L1), H2A family member Z (H2AFZ) and CXCL2 may be the important protein molecules involved in CXCL3-related tumor biology." (PMID 38031087, 2023). "Based on this conclusion, we further employed ERK blocker PD98059 to assess whether upregulation of CXCL3 expression enables tumor cells to specififically activate ERK signal pathway that facilitates the process of COAD." (PMID 38031087, 2023). "In addition, CXCL3 promotes blood vessel formation, tumor cell growth, cancer cell migration, cluster of differentiation (CD) 31 vascular cell infiltration, and smooth muscle cell migration." (PMID 37445610, 2023). "CXCL3 acts on the CXCR2 receptor, whereas CXCL6 acts on both CXCR1 and CXCR2 receptors, ultimately resulting in the recruitment of tumor-associated neutrophils and the promotion of tumor angiogenesis." (PMID 37161430, 2023). "Similar tumor-promoting effects were also found in the CXCL3/CXCR2 axis." (PMID 36612163, 2022). "CXCL2 and CXCL3 were differentially expressed at different tumor stages." (PMID 34269159, 2021). "sST2 secretion and the amount of CXCL3 in tumor tissues were measured using ELISA." (PMID 32340025, 2020). "One such gene seemed to be Cxcl3, which was identified by analysis of the expression of cytokines and chemokines; that is, Cxcl3 expression was suppressed in sST2-downregulated orthotopic tumor tissues." (PMID 32340025, 2020).
tumor (continued). "Therefore, the chief aim of this study was to assess the feasibility of using in vivo the pro-migratory chemokine Cxcl3 as an agent able to reduce the frequency of tumor lesions and, hence, to contrast the development of MB." (PMID 28018222, 2016). "Since the tumor lesions present at 2 months of age in Ptch1+/-/Tis21-/- mice develop invariably into a MB, these data represent a proof of concept that the treatment with Cxcl3 can reduce MB formation." (PMID 28018222, 2016). "However, the impact of CCL20 on the tumor immune microenvironment is weaker than that of CXCL3." (PMID 40179015, 2025). "Notably, Vegfa macrophages and Proinflammatory macrophages exhibited downregulation of tumor angiogenesis and protumorigenic genes (e.g., Cxcl3, Cxcl1, S100a8, SPP1) and upregulation of immune cell recruitment‐associated genes (e.g., Cxcl9, Ccl5, Ccl8) in mRNA‐treated groups." (PMID 39761175, 2025). "However, in Balb/C mice, CXCL3 demonstrated a stronger tumor inhibitory effect than did CCL20." (PMID 40179015, 2025). "We found that compared with orthotopic tumor growth, subcutaneous implantation resulted in significantly increased tumor growth, accompanied by downregulation of anti‐inflammatory adiponectin (AdipoQ) expression, activation of NF‐κB, upregulation of Cxcl3 expression, and accumulation of N2 TANs." (PMID 40751595, 2025). "Through single-cell transcriptomic sequencing, we discovered that the monocyte_C02 subpopulation is more prevalent in right-sided colorectal cancer, and its highly expressed genes, such as CXCL8, TNFAIP6, CXCL3, and SPP1, may be implicated in tumor growth promotion." (PMID 38711918, 2024). "Interaction of CXCL3 with its receptors not only induces the formation of new blood vessels but also facilitates the proliferation of tumors and the secretion of proteolytic enzymes, which disrupt the extracellular matrix and basement membrane, facilitating tumor invasiveness." (PMID 35664357, 2022). "In addition, CXCL3 attracts neutrophils in vivo and inhibits tumor growth." (PMID 32903444, 2020). "Besides that, high CXCL3 and ELF5 expression was also significantly related to vascular invasion, and low PHLPP2 expression was significantly associated with vascular invasion and tumor stage." (PMID 29209625, 2017). "CRNDE drives HCC progression by enhancing tumor growth, recruiting G-MDSCs, and inhibiting T cell invasion via TLR3 binding, NF-κB activation, and CXCL3 upregulation." (PMID 40352941, 2025). "We compared the effects of CXCL3 and CCL20 on tumor progression and found that knocking down either CXCL3 or CCL20 substantially inhibited tumor progression in both Balb/C mice and nude mice." (PMID 40179015, 2025). "Compared to adjacent normal cells, tumor colonocytes overexpressed chemokines (CXCL1, CXCL2, CXCL3, and CCL20), showing significant effects on inflammatory processes and immune cell recruitment." (PMID 40240912, 2025). "It is also possible that inhibition of a tumor–MDSC interaction was interrupted after BRD4 inhibition, as additional tumor-secreted soluble factors, including chemokines (CCL2, CXCL3, and CXCL5), were all reduced after BRD4 inhibition in vitro." (PMID 40762981, 2025). "To clarify the effect of CXCL3 on ICB therapy, we established a subcutaneous tumor model in BALB/c mice." (PMID 40179015, 2025). "The metabolite upregulated CXCL3 expression by activating the JAK2/STAT3 signaling pathway, thereby promoting the infiltration of PMN-MDSCs in TME and inhibiting anti-tumor immune function of CD8+ T-cells." (PMID 41226585, 2025). "The homologous receptor of CXCL3 is CXCR2, which is crucial for the migration of PMN-MDSCs from the bone marrow to the tumor." (PMID 40179015, 2025). "Analysis using the TIMER database demonstrated a positive correlation between CXCL3 expression and immune cell infiltration, including macrophages, neutrophils, B cells, CD4+ T cells, CD8+ T cells, and dendritic cells within the tumor microenvironment." (PMID 41259383, 2025).
tumor (continued). "Stimulated ESCC tumor cells to release more CXC chemokines CXCL2 and CXCL3 and enhanced the killing ability of neutrophils." (PMID 39906741, 2024). "RT-qPCR results showed increased expression of CXCL2, CXCL3, and CXCL5 in tumor tissues after MC-LR exposure." (PMID 39273011, 2024). "Our study emphasized the role of IL6high CAF on tumor cells for elevating level of various cytokine genes including IL6, IL32, IL33, CXCL1, CXCL3 and CXCL8, and oncogenic pathways, such as the Wnt and VEGF signaling pathways." (PMID 38892065, 2024). "Meanwhile, IL-17 stimulated ESCC tumor cells to release more CXC chemokines CXCL2 and CXCL3, which are involved in neutrophil migration." (PMID 39906741, 2024). "IL-17A produced by neutrophils exacerbates tumor growth by inducing CXC chemokines (CXCL1, CXCL2, CXCL3, CXCL5, CXCL8, and CXCL11) in gastric cancer cells to recruit neutrophils to the invasive edge." (PMID 39906741, 2024). "High variability genes in monocyte_C02 cells, including CXCL8, TNFAIP6, CXCL3, and SPP1, indicate a potential role in tumor promotion." (PMID 38711918, 2024). "Both CXCL1 and CXCL3 genes, along with CCL22, are involved in the chemotaxis of tumor cells and stromal cells within the surrounding microenvironment, which is essential in tumor dissemination during progression and metastasis." (PMID 39408697, 2024). "By RT-qPCR, we revalidated the expression of CXCLs (CXCL2, CXCL3, CXCL5, CXCL10) in MB49 YAP1-Sh clones and tumor tissues from VP-treated mice bearing UCB cell–derived xenografts." (PMID 39630608, 2024). "CXCL3 is upregulated in COAD and plays a crucial role in the control of malignant behaviors of tumor cells, which indicated its involvement in the pathogenesis of COAD." (PMID 38031087, 2023). "Thus, the immune chemokines CXCL8, CXCL3, and CCL20, which are positively associated with SLC7A11, have SLC7A11-like functions in the development of tumours and provide evidence of association at the tumour immune microenvironment level for poor prognosis in ACC patients with SLC7A11high." (PMID 37919768, 2023). "IDO1, NOX1, CXCL3, IL1RL2 and NOS2 were upregulated, as their expression levels were lower in the healthy group and higher in the tumor group." (PMID 36911403, 2023). "Furthermore, higher expressions of CXCL1, CXCL3, and CXCL8 in the high UVRAG expression group also indicated that UVRAG expression had a relationship with promoting tumor progression, angiogenesis, and immune suppression by recruiting tumor-associated macrophages (TMAs)." (PMID 37173968, 2023). "In MC-38 tumor grafts, using the same experimental set-up as in RM-9, radiation increased mRNA levels of CXCL1, CXCL2, CXCL3, and CXCL5 at 24 h post-treatment and protein levels of CXCL5 at 24 h and 48 h post-treatment." (PMID 38067390, 2023). "Previous studies have also shown that the immune chemokines CXCL3 and CCL20 also play an important role in tumour growth, invasion, and migration." (PMID 37919768, 2023). "In addition, our results showed that CXCL3 overexpression also exerts its role to regulate Bcl-2, Bcl-2/Bax and Cyclin D1 expression that are responsible for apoptosis and cell cycle, the processes upon which tumor cells depend for proliferation, survival, and metastasis." (PMID 38031087, 2023). "Our results showed that pro-inflammatory and tumor-promoting factors MMP9, IL-8, OSM, IL-1β, TNF-α, CXCL3, and ROS all increased to varying degrees after OCOs stimulation." (PMID 37644468, 2023). "In the RM-9 tumor model, radiation increased mRNA levels of CXCL2, CXCL3, and CXCL7 at 24 h post-treatment and the protein levels of CXCL1 and CXCL2 at 24 h and 48 h post-treatment." (PMID 38067390, 2023). "MMP9_macro expressed genes related to inflammatory chemokines (CXCL2, CXCL3, CXCL8) and genes like MMPs (MMP19, MMP9), which play an important role in tumor tissue remodeling." (PMID 35935940, 2022).
tumor (continued). "Exploration of the expression network indicated that inflammatory genes (CXCL8, CXCL3, PIGR, and RNASE1) and Wnt pathway genes (GAST, REG1A, TFF3, and ZG16B) are upregulated in tumor stem cells of UGICs." (PMID 35646860, 2022). "In melanoma tumor, the level of CXCL1, CXCL2, and CXCL3 is significantly elevated, accompanied by proangiogenic activity." (PMID 36612163, 2022). "The activation of Stat3 induced the secretion of glutamic acid-leucine-arginine (ELR) motif CXCLs (CXCL1, CXCL2, CXCL3 and CXCL8) in tumor cells." (PMID 35280694, 2022). "With marked patient occupancy (GBC6), Macro04 exhibited versatile tumor-promoting roles, including cytokine production (e.g., TNFAIP3, CXCL3), pro-angiogenesis (e.g., VEGFA), and ECM remodeling (e.g., SPP1) 28,36,37." (PMID 36198671, 2022). "Compared to fibroblasts from normal tissues, the top upregulated genes in tumor-derived fibroblasts were CXCL8, CXCL2, CCL2, CXCL3 and CXCL1, and the top downregulated genes were IGFBP5, PTGDS, CCN5, CFD, and RAMP1." (PMID 36357663, 2022). "NF-κB-mediated chemokine secretion bridges tumor cells and cells in the TME, and CXCR2 ligands (CXCL2 and CXCL3) enhance MDSC chemotaxis in advanced PCa9,16,18." (PMID 36435834, 2022). "Cancer cell-derived sST2 upregulates CXCL3 by inhibiting IL-33-ST2L signaling in the pancreatic cancer microenvironment and enhances tumor growth." (PMID 35802745, 2022). "For instance, it was found that the chemokines C-X-C motif ligand 1, 2, 3, and 8 (CXCL1, CXCL2, CXCL3, and CXCL8) are overexpressed in melanomas, which is accompanied by increased proliferation of tumor cells and tumor metastasis." (PMID 34885171, 2021). "The transcription level of CXCL3 was significantly higher in HNCC patients than healthy people in subgroup analyses based on gender, age, disease stages and tumor grade." (PMID 34870709, 2021). "The chemokine receptor CXCR2 and its ligands CXCL1, CXCL2, CXCL3, CXCL5 and CXCL8 play critical roles in the chemoattraction of neutrophils towards tumor tissues." (PMID 34429454, 2021). "Our findings suggest CXCL3 is significantly expressed in all stages of CRC and is mostly up regulated in all tumor samples." (PMID 34083590, 2021). "In order to determine the mechanism of neutrophils recruitment into the tumour, we screened neutrophil attracting chemokines (CXCL1, CXCL2, CXCL3, CXCL5, CXCL8 and CXCL12)." (PMID 32778818, 2020). "It is possible that a decrease in sST2 in the orthotopic tumor microenvironment activates IL-33/ST2L signaling in stellate cell-TAM or CAF-TAM interactions, which results in the suppression of Cxcl3 expression." (PMID 32340025, 2020). "The hub gene ADCY6, CXCL3, NPBWR1, TAS2R38, and PTGDR2 highly influence the clinical traits of age, histology types, neoplasm histologic grade, and overall survival in ESCA and READ, leading to their similarity in these clinical traits." (PMID 33552958, 2020). "It is recruited to the tumour microenvironment by chemokines such as CXCL8,CXCL1,CXCL2, and CXCL3 by the production of inflammatory mediators such as TNF-Alfa, MIP-1 ALFA, H202, and NO that are cytotoxic to tumour cells." (PMID 28275390, 2017). "The differentially enriched regions for active histone marks also included the loci for the neutrophil chemoatractants Cxcl3/5, and the interferon-response induced Ifitm1/2/3, which were higher in the SCC tumours." (PMID 28387316, 2017). "CXCL3 expression was up-regulated in the HCC tumor tissues, and HCC patients with higher CXCL3 expression displayed a poorer prognosis." (PMID 27255419, 2016). "CXCL1, CXCL2, and CXCL3 expression was higher and CXCR1 expression was lower in tumor tissues during HCC progression compared with the controls." (PMID 27682863, 2016). "Several genes were up‐regulated in tumor tissues during the progression period, including CXCL1, CXCL2, CXCL3, and IL‐1β, while CXCR1 expression was down‐regulated." (PMID 27682863, 2016).